RBM15 (RNA binding motif protein 15)
Diseases named in the same sentence as RBM15 in open-access papers (continued):
Sharing a sentence is not in itself a finding about the gene and the disease.
leukemia (10 papers, 2015 to 2025). A malignant (clonal) hematologic disorder, involving hematopoietic stem cells and characterized by the presence of primitive or atypical myeloid or lymphoid cells in the bone marrow and the blood. "RBM15 has been extensively studied in pediatric leukemia, where chromosomal translocations of RBM15 are implicated in disease progression." (PMID 40953081, 2025). "This suggests that cooperating mutations are required to develop leukemia in the presence of RBM15::MKL1." (PMID 37325571, 2023). "In AML, increased WTAP and RBM15 expression (or writer proteins themselves) could block differentiation, leading to leukemia, whereas increased eraser expression could cause leukemia via separate pathways." (PMID 29061143, 2017). "In AML, this RBFOX2/m6A/RBM15/YTHDC1/PRC2 axis is essential for leukemia cell survival, proliferation, and the self-renewal and maintenance of leukemia stem/progenitor cells." (PMID 41403702, 2025). "The depletion of RBM15 in the human megakaryoblastic leukemia cell line Meg-01 enhances the formation of alternatively spliced isoforms of RUNX1a and GATA1s." (PMID 37325571, 2023). "One mechanism through which RBM15::MKL1 induces leukemia in vitro and in vivo is through aberrant binding and activation of RBPJ, which is essential for the differentiation bias toward megakaryocytes and proliferation of leukemic cells." (PMID 37325571, 2023). "RBM15 has crucial roles in maintaining quiescence in hematopoietic stem cells and in megakaryocyte leukemia cell line differentiation by controlling the splicing of key differentiation genes, including GATA1, RUNX1, TAL1, and c-MPL." (PMID 28081722, 2017). "We observed that affinity purified Flag-tagged RBM15 protein is more efficiently methylated than the R578K mutant in western blots (WBs) in transfected 293T cells (compare lanes 1 and 2) as well as in leukemia cells." (PMID 26575292, 2015). "Thus, dysregulation of PRMT1-–RBM15 pathway might be a common mechanism in leukemia and solid tumors." (PMID 26575292, 2015). "For example, RBM15::MKL1 overexpression decreases endogenous RBM15 levels and increases endogenous MKL1 expression in the megakaryoblastic leukemia cell line 6133, while RBM15 overexpression reduces the fusion protein expression." (PMID 37325571, 2023). "When the leukemia cells were treated with DB75 (a PRMT1 inhibitor), RBM15 methylation was reduced." (PMID 26575292, 2015). "Although each of the major proteins in the m6A methylation complex—that is, RBM15, WTAP, METTL3, and METTL14—show alterations in myeloid leukemias, definitive demonstration of the role of m6A will require mechanistic evidence linking m6A alterations to leukemia phenotypes in these cancers." (PMID 28081722, 2017). "Consistently, PRMT1 knockdown increased RBM15 protein level but not the RBM15 mRNA level in MEG-01 cells as well as in other leukemia cells (data not shown)." (PMID 26575292, 2015).
lung carcinoma (10 papers, 2021 to 2026). "RBM15 deficiency induced ferroptosis in lung cancer through altering TGF-β/Smad2 pathway." (PMID 40682199, 2025). "Notably, RBM15’s potential to promote the malignant behavior of lung cancer is linked to its antagonistic relationship with SETD2, a recognized favorable prognostic indicator for LUAD." (PMID 38915367, 2024). "To clarify the role of RBM15 in lung cancer, we measured RBM15 expression in various lung cancer cell lines." (PMID 40923717, 2026). "This work expands the understanding of post-transcriptional regulation in lung cancer and identifies the RBM15/IGF2BP2-PTPRH axis as a potential therapeutic target for NSCLC intervention." (PMID 42113318, 2026). "Recently, a seven-gene m6A/m5C risk model, comprising METTL3, NPLOC4, RBM15, YTHDF1, IGF2BP1, NSUN3, and NSUN7, was developed to stratify the prognosis of early-stage lung cancer." (PMID 40279954, 2025). "In lung cancer, accumulating evidence has demonstrated that RBM15 acts as a pro-tumorigenic factor that drives malignant progression, particularly in non-small cell lung cancer (NSCLC)." (PMID 41403702, 2025). "RBM15 is consistently overexpressed in lung cancer cells, and its silencing markedly reduces cell viability, suppresses proliferation, invasion, and migration, while also restraining tumor growth in xenograft mouse models." (PMID 41403702, 2025). "Together, these results underscore RBM15 as a mediator of both metabolic reprogramming and immune evasion in lung cancer." (PMID 41403702, 2025). "The proposition of targeting RBM15 opens new avenues for future directions in lung cancer treatment." (PMID 38915367, 2024). "Knockdown of RBM15 significantly increases Fe2+ and lipid peroxidation, promotes ferroptosis, and inhibits lung cancer cell growth." (PMID 39039611, 2024). "The results showed that the expression profiles of eight m6A regulators (ALKBH5, FTO, HNRNPC, METTL14, RBM15, YTHDC1, YTHDC2, and ZC3H13) were significantly different among the three different lung cancer subtypes (P < 0.01)." (PMID 34805165, 2021).
colorectal cancer (9 papers, 2020 to 2025). A primary or metastatic malignant neoplasm that affects the colon or rectum. "We found that mutant RBM15 significantly linked to higher MSI MANTIS scores in colorectal cancer, supporting the role of RBM15 in regulating tumor immunomodulation." (PMID 40370450, 2025). "In addition, RBM15 knockdown caused a slight reduction of cell proliferation in either human or murine colorectal cancer cells." (PMID 40370450, 2025). "Furthermore, high expression of RBM15 was associated with poor prognosis in colorectal cancer patients." (PMID 40370450, 2025). "We found that RBM15 is overexpressed in colorectal cancer and is associated with poor prognosis." (PMID 40370450, 2025). "Overall, our study identifies RBM15 as a potent suppressor of anti-tumor immunity and highlights RBM15 as a promising therapeutic target for restoring immune surveillance in colorectal cancer." (PMID 40370450, 2025). "Here we identify a cancer cell-intrinsic mechanism by which RBM15 suppresses the tumor immune response in colorectal cancer." (PMID 40370450, 2025). "Consistently, the infiltration levels of CD8+ T cells and DCs were markedly higher in human colorectal cancer tumors with genetic alterations leading to deep depletion of RBM15." (PMID 40370450, 2025). "To unravel the gene expression alterations induced by RBM15, we performed bulk RNA sequencing (RNA-seq) in RBM15 KO and wild-type (WT) colorectal cancer HCT15 cells." (PMID 40370450, 2025). "Our analysis revealed that RNA binding motif protein 15 (RBM15) is highly expressed in colorectal cancer and correlates with poor patient prognosis." (PMID 40370450, 2025). "This study also provides a compelling rationale for establishing RBM15 as a promising therapeutic target for colorectal cancer." (PMID 40370450, 2025). "Overall, these findings suggest that RBM15 overexpression is negatively correlated with immune cell infiltration in colorectal cancer, presenting an immunosuppressive function of RBM15 in colorectal tumor microenvironment." (PMID 40370450, 2025). "In this study, we reveal a cancer cell-intrinsic function of RBM15 in driving immune evasion in colorectal cancer." (PMID 40370450, 2025). "Collectively, these findings suggest that RBM15 depletion significantly affects carbon metabolism and upregulates the expression level of FH, which in turn downregulates fumarate in colorectal cancer." (PMID 40370450, 2025). "Strikingly, we found that FH expression was significantly upregulated in human and murine colorectal cancer cells by RBM15 KO, which in turn led to a reduction in fumarate levels." (PMID 40370450, 2025). "To reveal the tumor-intrinsic functional role of RBM15 in colorectal cancer, we initially utilized the CRISPR/Cas9 gene editing system to knock out (KO) RBM15 in the human colorectal cancer cell line HCT15." (PMID 40370450, 2025). "RBM15 knockout significantly decreased the maximal mitochondrial respiration in both human and murine colorectal cancer cells." (PMID 40370450, 2025). "As proof, RBM15 knockdown suppressed colorectal cancer development by regulating the m6A levels in MYD88 mRNA." (PMID 39023191, 2024). "RBM15 silencing-mediated m6A methylation modification can inhibit the growth of colorectal cancer and prevent its liver metastasis." (PMID 39039611, 2024). "It was reported that knocking down RBM15 inhibits colorectal cancer cell proliferation and metastasis as reported." (PMID 37732317, 2023). "Consistent with previous research, increased RBM15 is also related to the development of tumors, such as colorectal cancer, laryngeal squamous cell cancer (LSCC) and pancreatic adenocarcinoma." (PMID 37732317, 2023). "Apart from that, overexpressing RBM15 could expedite colorectal cancer cell growth and migration by increasing KLF1 stability." (PMID 40883807, 2025). "Furthermore, RBM15 expression was significantly higher in colorectal cancer compared to adjacent normal tissues." (PMID 40370450, 2025).
colorectal cancer (continued). "Furthermore, it has been reported that RBM15-mediated m6A modification of MyD88 mRNA sustains MyD88 stability and accelerates the proliferative and invasive abilities of colorectal cancer cells." (PMID 40883807, 2025). "Furthermore, previous studies have demonstrated that elevated RBM15 could accelerate colorectal cancer cell growth and metastasis through m6A modification of MyD88 and KLF1 mRNA." (PMID 40883807, 2025). "RBM15 has been shown to enhance the stability and expression of KLF1 mRNA in colorectal cancer through IGF2BP3-mediated m6A modification." (PMID 39716068, 2024). "In colorectal cancer, KLF1 expression is upregulated by RBM15 through m6A modification." (PMID 39716068, 2024). "Furthermore, analysis of publicly available single-cell RNA datasets further demonstrated that there was a negative correlation between RBM15 expression and the CD8 T cell infiltration in tumors of colorectal cancer patients." (PMID 40370450, 2025).
clear cell renal cell carcinoma (8 papers, 2022 to 2025). "In clear cell renal cell carcinoma (ccRCC), RBM15 is highly expressed and promotes cell proliferation, colony formation, migration, invasion, and EMT." (PMID 41403702, 2025). "RNA binding motif protein 15 (RBM15) is involved in the methyltransferase complex and has been shown to impact the growth of various tumours, notably clear cell renal cell carcinoma." (PMID 39580709, 2024). "RBM15 expression was positively correlated with immune-infiltrating cells in renal clear cell carcinoma (KIRC), brain low-grade glioma (LGG), and pancreatic adenocarcinoma (PAAD)." (PMID 36389678, 2022). "In addition, in clear cell renal cell carcinoma, high RBM15 expression is mainly attributed to histone H3 acetylation at its promoter region, mediated by the histone acetyltransferases EP300/CBP." (PMID 41403702, 2025). "Moreover, in clear cell renal cell carcinoma (ccRCC) tissue, RNA-binding motif protein 15 promoted M2 polarization by enhancing the stability of CXCL11 mRNA in an m6A-dependent manner, which resulted in ccRCC progression." (PMID 39548525, 2024). "RBM15 enhances the growth, metastasis, and infiltration of clear cell renal cell carcinoma." (PMID 37474926, 2023).
acute myeloid leukemia (6 papers, 2017 to 2025). Acute myeloid leukemia (AML) is a group of neoplasms arising from precursor cells committed to the myeloid cell-line differentiation. "Importantly, RBM15 plays a pivotal role in hematopoietic system development, and its dysregulation has been strongly linked to hematological malignancies such as acute myeloid leukemia (AML)." (PMID 41403702, 2025). "Based on the evaluation of all these findings together, acute myeloid leukemia with RBM15::MRTFA(MKL1) fusion diagnosis was made, and the diagnosis for soft tissue lesion was revised to myeloid sarcoma." (PMID 38374236, 2025). "RBM15::MRTFA is among the recurring translocations defining acute myeloid leukemia." (PMID 38374236, 2025). "RBM15 is an RNA-binding protein that plays a pivotal role in the initiation and maintenance of acute myeloid leukemia (AML)." (PMID 41403702, 2025). "The RBFOX2/m6A/RBM15/YTHDC1/PRC2 axis plays an important role in myeloid leukaemia, with downregulation of RBFOX2 notably inhibiting acute myeloid leukaemia (AML) cell survival/proliferation and promoting myeloid differentiation of AML cells." (PMID 37640841, 2023). "However, a diagnosis of acute myeloid leukemia can be rendered regardless of blast count in the WHO 2022 classification if RBM15::MRTFA can be demonstrated with genetic studies." (PMID 38374236, 2025).
colon cancer (6 papers, 2020 to 2025). "In summary, RBM15 promotes colon cancer development through m6A-dependent stabilization of oncogenic targets such as ITGBL1 and TMC5, while activating the JAK–STAT signaling pathway." (PMID 41403702, 2025). "Broader genomic analyses of colon cancer (CC) have identified RBM15 among five critical m6A-related genes, including WTAP, CBLL1, and YTHDC2." (PMID 41403702, 2025). "Moreover, RBM15 depletion downregulates JAK–STAT pathway proteins, suggesting that RBM15 promotes colon cancer progression via JAK–STAT signaling." (PMID 41403702, 2025). "Knockdown of RBM15 suppressed the proliferation and metastasis of colon cancer cells." (PMID 36299451, 2022). "In colon cancer cell lines, METTL3 and RBM15 were downregulated, whereas transcript levels of FTO and ALKBH5 were upregulated." (PMID 38665783, 2024).
ovarian carcinoma (6 papers, 2021 to 2025). A malignant neoplasm originating from the surface ovarian epithelium. "RBM15 recruits the complex to specific RNA locations by binding the m6A complex, and its increased expression is associated with ovarian cancer metastasis." (PMID 37194218, 2023). "We found decreased YTHDC1 and increased RBM15 expressions were associated with ovarian cancer cell metastases and HNRNPC was a predictor of paclitaxel resistance." (PMID 33225598, 2021). "This suggests to us that RBM15 may be associated with a favorable prognosis in ovarian cancer." (PMID 38915367, 2024). "Yuan demonstrated that RBM15 regulates m6A modifications by binding to target RNAs and recruiting the methyltransferase complex, thereby influencing ovarian cancer cell resistance to PTX." (PMID 40719884, 2025). "Activation of the TGF-β/Smad pathway was shown to interact with the RBM15 promoter and directly inhibit RBM15 expression in PTX-resistant ovarian cancer cells." (PMID 38915367, 2024). "UBA6-AS1 curbed UBA6 self-degradation through m6A modification mediated by RBM15, thereby effectively impeding ovarian cancer proliferation, invasion, and metastasis." (PMID 38915367, 2024). "While controversy surrounds RBM15’s role in ovarian cancer, these findings suggest the potential for a future role wherein RBM15 acts as a tumor suppressor or a tumor suppressor cofactor." (PMID 38915367, 2024). "We found that a decrease in YTHDC1 and an increase in RBM15 expressions were correlated with ovarian cancer cell metastases." (PMID 33225598, 2021). "We also noticed that decreased expression of YTHDC1 and increased expression of RBM15 were correlated with the status of ovarian cancer cell metastasis (GSE73168 and GSE30587)." (PMID 33225598, 2021). "Given the theory implicating the distal oviduct as a common source for epithelial ovarian cancer, we analyzed the GSE69428 data and showed that the expression of IGF2BP2, IGF2BP3, RBMX, YTDHF1, and RBM15 was also higher in ovarian cancer than in normal oviduct." (PMID 33225598, 2021). "The m6A regulators RBM15, ZC3H13, YTHDF1, and IGF2BP1 may cause ovarian cancer immune infiltration." (PMID 37194218, 2023). "For example, the expression of HNRNPA2B1 was positively correlated with the expressions of IGF2BP3, YTHDC1, YTHDF2, RBM15, and ZC3H13 in ovarian cancer." (PMID 33225598, 2021). "LncRNA ubiquitination modifier activator 6 antisense RNA1 (UBA6-AS1) recruits RBM15 to mediate UBA6 m6A methylation, and IGF2BP1 enhances UBA6 stability by recognizing its m6A modification, ultimately encouraging ovarian cancer cell proliferation, invasion, and migration." (PMID 37194218, 2023). "Two GEO databases demonstrated that 7 readers (HNRNPC, IGF2BP1, IGF2BP2, IGF2BP3, RBMX, YTHDC2, and YTHDF2) and 3 writers (METTL3, RBM15, and RBM15B) were more highly expressed in ovarian cancer than in ovarian surface epithelium or normal peritoneum tissues (GEO14407 and GEO12470)." (PMID 33225598, 2021).
pancreatic adenocarcinoma (6 papers, 2022 to 2025). "In pancreatic adenocarcinoma (PAAD), RBM15 overexpression is closely linked to patient survival and shows positive correlation with immune infiltration and immune checkpoint markers." (PMID 41403702, 2025). "Importantly, in pancreatic adenocarcinoma (PAAD), overexpression of RBM15 is associated with patients’ OS, DFI, PFI, or DSS." (PMID 35223996, 2022).
prostate carcinoma (6 papers, 2020 to 2026). A carcinoma that arises from epithelial cells of the prostate gland. "Together, these data suggested that RBM15 was responsible for the m6A methylation of R-loops in prostate cancer." (PMID 38658974, 2024). "We found that the CNVs patterns of HNRNPC, METTL3, RBM15, ALKBH5 and FTO (one reader, two writers, and two erasers) were notably associated with RFS of prostate cancer." (PMID 32710725, 2020). "Specifically, copy number loss of HNRNPC, METTL3, and FTO were significantly correlated with poor survival of prostate cancer, while patients with copy number gain of RBM15 and ALKBH5 had worse RFS." (PMID 32710725, 2020). "Further evaluation of the mechanism for the RBM15/IGF2BPs/SEMA3F axis may provide a new strategy for prostate cancer." (PMID 38658974, 2024). "Given the similar expression patterns and effects on R-loop metabolism, we assume IGF2BPs and RBM15 could function as tumor suppressor in prostate cancer." (PMID 38658974, 2024). "Furthermore, RBM15 depletion also impairs the biological function of IGF2BPs in prostate cancer." (PMID 38658974, 2024). "More importantly, our study provides a novel RBM15/IGF2BPs/DNMT1 trans-omics regulation m6A axis, indicating the new crosstalk between RNA m6A methylation and DNA methylation in prostate cancer." (PMID 38658974, 2024). "Altogether, our data showed that RBM15 and IGF2BPs play tumor suppressor roles via SEMA3F-mediated regulation of Hippo pathway in prostate cancer." (PMID 38658974, 2024). "In addition, our research provides a novel RBM15/IGF2BPs/DNMT1 trans-omics regulation m6A axis, indicating the new crosstalk between RNA m6A methylation and DNA methylation in prostate cancer." (PMID 38658974, 2024). "In prostate cancer, m6A modification level was upregulated, and the expression levels of METTL3, METTL14, VIRMA, RNA binding motif protein 15 (RBM15), HNRNPC, HNRNPA2B1, YTHDC2, YTHDF1 and YTHDF2 increased." (PMID 37701836, 2023).
chronic myelogenous leukemia (5 papers, 2020 to 2023). "Consistent with our results, previous studies have demonstrated that RBM15 is upregulated in chronic myelogenous leukemia." (PMID 32582536, 2020). "Knockdown of RBM15 slows cell growth and induces apoptosis in chronic myelogenous leukemia cells." (PMID 34804951, 2021). "Knockdown of RBM15 could induce G1 → S phase arrest in chronic myelogenous leukemia cells." (PMID 34804951, 2021).